NOS2 (nitric oxide synthase 2)
Diseases named in the same sentence as NOS2 in open-access papers (continued):
Sharing a sentence is not in itself a finding about the gene and the disease.
glaucoma (14 papers, 2007 to 2025). Increased pressure in the eyeball due to obstruction of the outflow of aqueous humor. "NOS2 is implicated in retinal ganglion cell degeneration in a rat glaucoma model in which intraocular pressure (IOP) is experimentally elevated by blood vessel cauterization, but not in a rat glaucoma model where IOP was elevated by injection of hypertonic saline." (PMID 18093296, 2007). "One study reported a correlation between a regulatory region of the NOS2 gene and the development of primary open angle glaucoma." (PMID 18093296, 2007). "Here we tested the involvement of NOS2 in glaucomatous neurodegeneration using the inherited DBA/2J model of glaucoma." (PMID 18093296, 2007). "Further experiments involving various models are needed to assess the general importance of Nos2 in glaucoma." (PMID 18093296, 2007). "There are multiple possible explanations for the differences in the observed role of NOS2 in glaucoma in these studies, including differences in genetically determined risk factors between the animals that were used." (PMID 18093296, 2007). "We used both genetic ablation and pharmacological inhibition of NOS2activity to test the involvement of NOS2 in glaucomatous damage to the optic nerve and retina in this inherited glaucoma model." (PMID 18093296, 2007). "In contrast to our results, Neufeld and colleagues have proposed an important role for NOS2 in glaucoma and suggested its inhibition as a treatment." (PMID 18093296, 2007). "NOS2 was reported to be induced in optic nerve glia during glaucoma, and involved in glaucomatous damage to the retina in a rat model of glaucoma." (PMID 18093296, 2007). "To test the importance of NOS2 for an inherited glaucoma, in this study we both genetically and pharmacologically decreased NOS2 activity in the DBA/2J mouse glaucoma model." (PMID 18093296, 2007). "GAS7 may interact with other genes implicated in glaucoma pathogenesis such as MYOC, OPTN, WDR36, CAV1, nitric oxide synthase 2 (NOS2), forkhead box C1 (FOXC1), apolipoprotein E (APOE), amyloid precursor protein (APP), and clusterin (CLU)." (PMID 32545285, 2020). "Further studies are required to assess the general importance of Nos2 in glaucoma." (PMID 18093296, 2007). "The possibility that NOS2 inhibition could be neuroprotective in glaucoma was strengthened by a report showing that NOS2 inhibition delays RGC degeneration after axotomy." (PMID 18093296, 2007). "The ability of a NOS2 inhibitor to protect RGCs from ischemia led to the suggestion that NOS2 inhibition may be protective in glaucoma." (PMID 18093296, 2007). "Complete deficiency of NOS2 did not prevent homozygous mutant mice from developing severe glaucoma, showing that NOS2 is not required for glaucomatous axon degeneration in the optic nerve." (PMID 18093296, 2007). "In glaucoma patients, NOS2 expression was found to be up-regulated in optic nerve head glia." (PMID 18093296, 2007). "Therefore, we continued to test the role of NOS2 in this glaucoma by both genetically and pharmacologically inhibiting its function." (PMID 18093296, 2007). "Thus, although we found no protective effect of NOS2 in the inherited DBA/2J model of glaucoma, it will be important to study the role of NOS2 in settings that have a greater ischemic component." (PMID 18093296, 2007). "Therefore, pharmacological neuroprotection by NOS-2 inhibition, such as the use of aminoguanidine or blocking NOS-2 induction and gene expression, may be a promising approach for the treatment of patients with glaucoma." (PMID 37510790, 2023). "Although these expression studies provided no clear association between NOS2 and glaucoma, NOS2 is a powerful modulator of cell functions that may be transiently expressed by single cells." (PMID 18093296, 2007). "To determine the temporal and spatial expression pattern of Nos2 in DBA/2J mice, we examined RNA and protein levels in the optic nerve head at different stages of glaucoma." (PMID 18093296, 2007).
glaucoma (continued). "Nitric oxide synthase 2 (NOS2) contributes to neural death in some settings, but its role in glaucoma remains controversial." (PMID 18093296, 2007). "To further understand the consequences of the ketogenic diet on inflammation, we examined the expression of pro-inflammatory cytokine IL-6 and NOS2 in D2 glaucoma mice with or without the ketogenic diet." (PMID 30424795, 2018). "NOS-2 activity has generally been thought to be negative in the context of glaucoma since NOS-2 induced by ocular hypertension can lead to protein nitration." (PMID 23755225, 2013). "Despite the presence of a few NOS2 positive cells in the optic nerve head, NOS2 protein was not substantially increased during the glaucoma." (PMID 18093296, 2007). "Occasionally, NOS2 protein was detected in optic nerve cells with advanced glaucoma but not in unaffected optic nerves." (PMID 18093296, 2007). "The general importance of NOS2 in glaucoma was recently questioned by studies that do not support a role for NOS2 in another model of glaucoma." (PMID 18093296, 2007). "In some but not all studies, increased expression of Nos2 is reported in glaucoma patients and rat models of glaucoma." (PMID 18093296, 2007). "This might not have significant implications for glaucoma pathology since it has been shown that either knocking out NOS-2 on the DBA/2J background or inhibiting NOS-2 with aminoguanidine conferred no protection of RGCs or their axons." (PMID 23755225, 2013). "However, neither the complete genetic ablation nor the treatment with an inhibitor of NOS2 had any affect on the severity or incidence of this glaucoma." (PMID 18093296, 2007). "We clearly demonstrate that glaucoma can manifest even when NOS2 is completely absent." (PMID 18093296, 2007). "Although our studies have not assessed if other nitric oxide synthases could have compensated for the absence of NOS2, as has been suggested in other systems, our results do not support a damaging role of NOS2 in this mouse model of glaucoma." (PMID 18093296, 2007). "Neurodegeneration in glaucoma might result from interactions between T cells and microglia that they activate, leading to the release of substances harmful to RGCs, such as TNF-α and nitric oxide synthase-2, as validated in both rodent models and human post-mortem glaucoma tissues." (PMID 41403938, 2025). "Thus, the general importance of NOS2 induction for glaucoma is not certain." (PMID 18093296, 2007). "To better understand our findings in light of these reports, and to assess whether aminoguanidine has off-target effects that protect against glaucoma by a mechanism that is independent of NOS2, we tested the ability of aminoguanidine treatment to alleviate the glaucoma of DBA/2J mice." (PMID 18093296, 2007). "It was shown that NOS-2 is absent in healthy patients, while NOS-1 and NOS-3 are upregulated in glaucoma patients." (PMID 25914734, 2015).
rheumatoid arthritis (14 papers, 2006 to 2026). A chronic, systemic autoimmune disorder characterized by inflammation in the synovial membranes and articular surfaces. "NOS2 is also part of the “Role of macrophages in rheumatoid arthritis” and “LXR/RXR activation” pathways." (PMID 31969876, 2019). "GATA1 induces rheumatoid arthritis development by promoting the transcriptional activation of NOS2." (PMID 40650665, 2025). "Additionally, CRT demonstrated potential in treating rheumatoid arthritis by regulating the PI3K/HIF1α/NOS2 signaling pathway." (PMID 39130629, 2024).
ischemia (13 papers, 2007 to 2025). A hypoperfusion of the BLOOD through an organ or tissue caused by a PATHOLOGIC CONSTRICTION or obstruction of its BLOOD VESSELS, or an absence of BLOOD CIRCULATION. "The concentrations of Il‐6, Tnfα, Il‐16, Fcgr3α, and Nos2 were elevated following ischemia/reperfusion, which were partially mitigated by RF." (PMID 39915908, 2025). "Induction of NOS2 is relevant because administration of an NOS2 inhibitor partially protects against retinal thinning after ischemia and diabetic retinopathy, and NOS2−/− mice are resistant to diabetic retinopathy." (PMID 19626134, 2009). "It will be important to assess ischemic markers in the various models to help determine if ischemia is more severe in the cauterization model and if this explains the differential efficacy of NOS2 inhibition." (PMID 18093296, 2007). "Almost all these studies used the mutant in various models for brain pathologies such as ischemia, Alzheimer's or Parkinson's disease, focusing on the role of NOS2 induction in the long-term outcome of the insult." (PMID 17786214, 2007). "Since NOS2 could play central roles in inflammation mediated by microglia and macrophages in the central nervous system, it will be interested to know whether the similar pathways are involved in NOS2 induction in other inflammatory cells after ischemia or FC treatment." (PMID 23029446, 2012). "On the other hand, astroglial NO production has been demonstrated mainly as a reaction to various detrimental stimuli such as ischemia or inflammation, through the activity of a stress-induced NOS isoform (NOS2) that can produce large amounts of NO, but on a much slower time scale [e.g. 3]–." (PMID 17786214, 2007).
lung carcinoma (13 papers, 2012 to 2025). "Several microRNAs are implicated in inflammation-associated carcinogenesis, and genetic ablation of NOS2 in a genetically engineered mouse model of KRAS-induced lung cancer reduced the expression of oncomir-21." (PMID 27367029, 2016). "The presence of a lower expression of mir-21 in NKPC tumors as compared with tumors in KPC mice is consistent with the reports suggesting an association between increased NOS2 and mir-21 in lung cancer." (PMID 27367029, 2016). "Furthermore, NOS2-deficiency decreased lung tumor growth and oncogenic Kras-mediated inflammatory response, and increased survival in a mouse model of lung cancer with conditional activation of mutant KRAS." (PMID 27367029, 2016). "Moreover, inhibition of NOS2 may have therapeutic value for lung cancer with oncogenic KRAS mutations." (PMID 35256890, 2022). "The A/J urethane model of lung cancer is unique among most murine lung tumor models in that TAMs surrounding late-stage ACs express high levels of NOS2 and little ArgI, indicating that they are primarily M1-programed." (PMID 25505466, 2014). "Additionally, NOS2/NO signaling is reported to mediate mutant KRAS-induced inflammation in lung cancer model, which is consistent with its role as an inflammatory mediator." (PMID 27367029, 2016). "Furthermore, we isolated F4/80+ TAMs from PBS- or HCQ-treated mice with orthotopic lung cancer, and we found that the M1-like molecules (Nos2, Ifng, IL12b,and IL1b) were up-regulated and the M2-like molecules (Arg1, Tgfb1, IL10, and Ido1) were down-regulated with HCQ treatment." (PMID 30373678, 2018). "In sum, our results thus far have demonstrated that CSCs expand in lung cancer tumoroids and tumors wherein the Wnt signaling pathway plays a crucial role in lung CSC development and this signaling involves several important known targets such as Sox2, ALDH, and Nos2." (PMID 31796785, 2019).
migraine (13 papers, 2013 to 2025). "This analysis revealed significant downregulation of NOS2 (inducible nitric oxide synthase) along with key migraine‐associated inflammatory factors, including TNF‐α, IL‐6 and CGRP." (PMID 41194575, 2025). "The analysis results showed that NOS2 SNV G2087A (rs2297518) was associated with a risk of migraines (p = 0.0120)." (PMID 32111088, 2020). "It was found that the carrier status of the NOS2 SNV G2087A (rs2297518) was associated with a risk of migraine." (PMID 32111088, 2020). "Carriers of the AA haplotype rs2779249 of the NOS2 gene showed a higher risk of developing other primary headaches: migraine (OR = 2.65 [95% CI: 1.34–5.22], p-value = 0.0027) in the Brazilian population, and cluster headache (χ2 = 5.21; p-value = 0.022) in the Swedish population." (PMID 36833440, 2023). "Experimental validation confirmed Mt2's dual regulatory function: its inhibition reduced NOS2 expression—a key mediator of vascular tone—and concurrently decreased migraine‐related inflammatory markers, including CGRP, IL‐6, and TNF‐α." (PMID 41194575, 2025). "This study observed that NOS3 rs743506 and NOS2 2087G/A interact significantly in patients with migraine compared to control (p < 0.05), and this combination impacts the susceptibility to migraine." (PMID 35627115, 2022). "The AA genotype for NOS2 SNV G2087A (rs2297518) and C(−1026)A (rs2779249) was associated with migraines with auras(p = 0.0349)." (PMID 32111088, 2020). "The endothelial‐specific knockdown of Mt2 suppressed neurovascular inflammatory cascades (NOS2, TNF‐α, IL‐6, CGRP), regulating the cerebrovascular tone and somatosensory cortical neuronal activation, contributing to the migraine‐like pain relief." (PMID 41194575, 2025). "However, the prognostic role of NOS1, NOS2, NOS3 genes in the development of the common AH + TTH phenotype has not been studied in comparison with the second most common phenotype (AH + migraine)." (PMID 33809023, 2021). "Specifically, Mt2 appears to integrate endothelial‐derived nitric oxide production (NOS2), cytokine/chemokine release (TNF‐α/IL‐6), and neuropeptide activity (CGRP) to gate vascular tone regulation and neuronal excitability, ultimately driving migraine‐like behavioral manifestations." (PMID 41194575, 2025).
ulcerative colitis (13 papers, 2011 to 2025). An inflammatory bowel disease involving the mucosal surface of the large intestine and rectum. "Ulcerative colitis appears to be caused by a disruption of intestinal homeostasis and integrity, while up-regulated NOS2 expression in gut mucosa has been shown to cause apoptosis of epithelial cells." (PMID 22073270, 2011). "The upregulation of NOS2 has been shown to exacerbate acute colitis, aligning with our findings where NOS2 expression was significantly elevated in ulcerative colitis samples." (PMID 41009970, 2025). "In short, Rauwolfia polysaccharide can inhibit the progress of ulcerative colitis through NOS2-mediated JAK2/STAT3 pathway." (PMID 38626146, 2024). "To further explore the role of NOS2 in LPS-induced ulcerative colitis, we designed and synthesized siNOS2-1, siNOS2-2 and siNOS2-3." (PMID 38626146, 2024). "NO, the product of NOS2 activity, is a well-recognized pro-inflammatory agent involved, for example, in ulcerative colitis." (PMID 31281314, 2019). "Interestingly, NOS2 was not only one of the differentially expressed genes for Jatrorrhizine-treated ulcerative colitis, but its expression level was negatively correlated with the relative abundance of Akkermansia." (PMID 36271438, 2022). "JA alleviates ulcerative colitis via regulating gut microbiota and NOS2 expression." (PMID 36271438, 2022). "Therefore, we speculate that Rau can inhibit the progress of ulcerative colitis through NOS2-mediated JAK2/STAT3 pathway." (PMID 38626146, 2024).
Alzheimer disease (12 papers, 2019 to 2026). A progressive, neurodegenerative disease characterized by loss of function and death of nerve cells in several areas of the brain leading to loss of cognitive function such as memory and language. "Subsequent proteomics revealed that 10 targets NOS2 to modulate Alzheimer's disease (AD)-associated pathways and the KEAP1-NRF2 axis." (PMID 42042200, 2026). "Brain region segmentation and morphometry in humanized apolipoprotein E (APOE) mouse models with a human NOS2 background (HN) contribute to Alzheimer’s disease (AD) research by demonstrating how various risk factors affect the brain." (PMID 38781243, 2024). "CASP9 and PTGS2 in neurodegeneration_multiple diseases, NOS1, NOS2 in Alzheimer disease pathway were identified as core targets." (PMID 37904435, 2023). "Studies of mouse models of Alzheimer's disease (AD) have demonstrated that nitric oxide synthase 2 (NOS2) is involved in AD pathology." (PMID 36647152, 2023). "Interestingly, several recent studies have reported that NOS2 differentially regulates Alzheimer’s disease (AD) pathology." (PMID 36647152, 2023). "The animals used were a triple transgenic Alzheimer’s disease model (3xTg-AD) in which the linalool-treated group (25 mg/kg, every 48 h, 3 months) showed a reduction in the inflammatory markers p38 MAPK, NOS2, COX-2, and IL-1β in the hippocampi and amygdalae." (PMID 37108100, 2023). "The Alzheimer disease pathway is the second-ranked signaling pathway, and 5 key targets, CASP9, APP, NOS2, NOS1 and PTGS2, are enriched in this pathway." (PMID 37904435, 2023).
Cerebral ischemia (12 papers, 2011 to 2024). Restriction of arterial blood supply to the brain associated with insufficient oxygenation to support the metabolic requirements of the tissue. "Cerebral ischemia results in NOS2 activation, leading to the production of nitric oxide which induces necrosis and apoptosis in the ischemic region." (PMID 34769397, 2021). "A previous study reported the protective role of Piperine in cerebral ischemia induced inflammation rat model by downregulating the expression of Cox-2, NOS-2 and NFKB." (PMID 33737876, 2020). "The inhibition of NOS2 expression in leukocytes and brain endothelial cells after cerebral ischemia can prolong treatment time and induce long-term neuroprotection." (PMID 32328128, 2020). "The expression of NOS2 in the cells of ischemic tissue and the surrounding potentially viable zone has been considered to be one of the factors that determine the distribution of tissue damage at the later stages of cerebral ischemia." (PMID 31640179, 2019).
ischemic stroke (12 papers, 2017 to 2025). A stroke disorder caused by obstruction of blood flow to the brain, due to thrombotic (local blood clot formation) or embolic (due to a blood clot or other material traveling from another site) event. "Immunostaining of the ischemic stroke regions showed that the expression of nitric oxide synthase 2 (NOS2), a proinflammatory cytokine and SASP, was significantly increased during cerebral IR injury and decreased by ABT263 treatment (ABT)." (PMID 34769397, 2021). "Some of the top20 most changed genes are already known to be relevant to the ischemic stroke physiopathology (e.g. Il-1R, Nos2, Prok2)." (PMID 30439964, 2018). "These combined results suggest that intravenous miR-122 mimic acted on both blood leucocytes and BMVECs from the luminal sides of vessels, and are consistent with previous reports that only combined deletion of NOS2 in blood cells and BMVECs prevents brain injury after ischemic stroke in rats." (PMID 30405345, 2018). "Two proteins, inducible nitric oxide synthase (NOS2) and glycogen synthase kinase-3 beta (GSK3B), were highlighted by the network pharmacology analysis, which may be the potential therapeutic targets for the GSTTF against ischemic stroke." (PMID 31640179, 2019).